KLF9 (KLF transcription factor 9)
Description:
Transcription factor that binds to GC box promoter elements. Selectively activates mRNA synthesis from genes containing tandem repeats of GC boxes but represses genes with a single GC box. Acts as an epidermal circadian transcription factor regulating keratinocyte proliferation.
Synonyms: BTEB; BTEB1
Tractability: Antibody: its Gene Ontology location is reachable by antibodies, with high confidence. PROTAC: ubiquitination databases record sites on it.
Gene: Protein-coding gene on chromosome 9 (70,384,604 to 70,414,657, reverse strand). Ensembl gene ENSG00000119138.
Subcellular location: Nucleus
Subcellular location (Human Protein Atlas): Nucleoplasm; Cytosol; Plasma membrane
Pathways (Reactome):
Cell-Cell communication: Positive Regulation of CDH1 Gene Transcription
Gene Ontology:
Molecular function: DNA-binding transcription factor activity; DNA-binding transcription factor activity, RNA polymerase II-specific; RNA polymerase II cis-regulatory region sequence-specific DNA binding
Biological process: cellular response to cortisol stimulus; circadian rhythm; negative regulation of keratinocyte proliferation; regulation of transcription by RNA polymerase II
Cellular component: nucleoplasm; nucleus; chromatin
Genetic constraint (gnomAD): Loss-of-function variants: 2 observed, 18.14 expected, observed/expected ratio (o/e) 0.11, 90% interval 0.044 to 0.35. The upper end of that interval is the gene's LOEUF score, 0.35, which puts it in group 1 of 6, group 1 being the genes least tolerant of losing a copy. Missense variants: 226 observed, 346.76 expected, observed/expected ratio (o/e) 0.65, 90% interval 0.58 to 0.73. Synonymous variants: 138 observed, 147.27 expected, observed/expected ratio (o/e) 0.94, 90% interval 0.81 to 1.08.
Homologues: Orthologues: chimpanzee KLF9 (100% identical), guinea pig KLF9 (99% identical), macaque KLF9 (98% identical), dog KLF9 (97% identical), rabbit KLF9 (97% identical), rat Klf9 (97% identical), mouse Klf9 (96% identical), pig KLF9 (95% identical), tropical clawed frog klf9 (67% identical), zebrafish klf9 (40% identical), Drosophila melanogaster luna (26% identical). Paralogues in human: KLF14 (40% identical), KLF13 (40% identical), KLF16 (36% identical), KLF11 (32% identical), SP9 (30% identical), KLF10 (30% identical), SP8 (29% identical), KLF12 (28% identical), SP5 (27% identical), KLF8 (27% identical), KLF5 (27% identical), SP7 (27% identical), and 10 more.
Diseases named in the same sentence as KLF9 in open-access papers:
KLF9 is named in the same sentence as 119 diseases in open-access papers, as found by Europe PMC text mining. Sharing a sentence is not in itself a finding about the gene and the disease. The quoted sentences say what the papers report.
endometrial cancer (17 papers, 2008 to 2025). Primary or metastatic malignant neoplasm involving the endometrium (mucous membrane that lines the endometrial cavity). "Over-expression of KLF9 in the human HEC-1-A endometrial cancer cell line implicated KLF9 in signaling TGF-β and in the induction of p21 (CDKN1A) (a tumor suppressor)." (PMID 38067370, 2023). "In another study, KLF9 expression was inversely associated with endometrial cancer metastasis, which involved, in part, the inhibition of Wnt/β-catenin signaling." (PMID 38067370, 2023). "Similar downregulation of KLF9 has been reported in endometrium cancer, where its downregulation is linked to estrogen-mediated growth control." (PMID 35047407, 2021). "Loss of Klf9 is associated with diminished fertility, embryo implantation defects and endometrial cancer." (PMID 23555910, 2013). "The role of KLF9 in endometrial cancer (EC) has attracted significant interest due to its association with tumor aggressiveness." (PMID 40860800, 2025). "The expression down-regulation of KLF9 has been demonstrated in numerous cancers including endometrial cancer, colorectal tumors, breast cancer, and hepatocellular carcinoma." (PMID 37833790, 2023). "In human HEC-1-A endometrial cancer cells, stable transfection with KLF9 caused the induction of the NR3C1 gene (Glucocorticoid Receptor, GR), suggesting the cross-regulation of KLF9 and GR." (PMID 38067370, 2023). "Over-expression of KLF9 in the endometrial carcinoma cell line HEC-1-A rendered these cells more proliferative to TGF-β." (PMID 38067370, 2023). "Briefly, KLF9 has been reported to be a target gene of miR-200c in human endometrial cancer cells and porcine adipocytes." (PMID 34438874, 2021). "For example, the expression of KLF9 was shown to be inversely correlated with endometrial tumor grade, and its silencing was further proposed to contribute to the etiology of endometrial cancer initiated by aberrant ESR1 signaling." (PMID 31821171, 2019). "In Ishikawa endometrial cancer cells, KLF9 opposed ER-α activity and decreased this protein's expression." (PMID 18783612, 2008). "Over-expression of KLF9 in the human endometrial cancer cell line HEC-1-A alters cell morphology, proliferative indices, and differentiation, when compared to KLF9 under-expressing HEC-1-A cells." (PMID 18783612, 2008). "However, in pathological states such as delayed labor, endometriosis, and endometrial carcinoma, KLF9 transcript levels (and corresponding protein) were reduced in relevant pathological tissues (myometrium, endometrium, endometrial tumors)." (PMID 40823902, 2025). "Indeed, the treatment of human Ishikawa endometrial cancer cells with estrogen stimulated their proliferation in vitro, an effect that was enhanced by the knock-down of KLF9." (PMID 38067370, 2023). "Underscoring the emerging role KFL9 in hormone-responsive neoplasms, knockout of Klf9 in mice increased overall endometrial carcinoma burden, while its ectopic expression promoted apoptosis in androgen-dependent prostate cancer cells and restricted BCa metastatic spread." (PMID 36823570, 2023). "In endometrial cancer cell line Hec-1-A, the stability of KLF9 expression could increase DNA synthesis and cell cycle dynamics by inducing cell cycle-related genes." (PMID 34612136, 2021). "Reports on the role of KLF9 are thus far limited to colon and endometrial carcinoma." (PMID 25593984, 2014). "Similarly, endometrial carcinomas also demonstrated lower levels of KLF9 when normal endometrium and stage I disease were compared with stage II – IV carcinomas." (PMID 25593984, 2014). "KLF9 is a repressor of estrogen receptor α actions on select nuclear target genes in Ishikawa endometrial cancer cells and this ability may contribute to aberrant cell growth responses in the face of ovarian estrogen stimulation, when KLF9 expression is lowered or absent." (PMID 38067370, 2023).
endometrial cancer (continued). "This same in vitro context identified positive links between KLF9 and the PKA and JNK pathways, and corresponding signaling in endometrial carcinoma HEC-1-A cells." (PMID 38067370, 2023). "In human Ishikawa endometrial cancer cells, MET treatment (60 μM) decreased cell numbers and elicited distinct temporal changes in ESR1, KLF9, PGR, PGR-B, KLF4, DKK1, and other tumor biomarker mRNA levels." (PMID 32046384, 2020). "Krüppel-like factor 9 (KLF9), also known as basic transcription element-binding protein 1 (BTE-B1), has been found downregulated in a number of cancers including endometrial carcinoma and colorectal cancer." (PMID 30348136, 2018). "In this regard, a recent study from our laboratories demonstrated the progesterone-dependent co-recruitment of KLF9 and the progesterone receptor to the SLPI promoter, concomitant with induction of this gene's expression, in Ishikawa endometrial cancer cells." (PMID 18783612, 2008). "Supporting this, multiple studies have reported substantially reduced KLF9 expression in aggressive cancer cell lines, particularly in prostate and endometrial carcinomas, when compared to non-malignant cells." (PMID 40860800, 2025).
endometriosis (17 papers, 2013 to 2025). The growth of functional endometrial tissue in anatomic sites outside the uterine body. "Given that endometriosis predisposes patients to cancers of the female reproductive tract, we first summarize the current state of knowledge on the involvement of KLF9 and KLF13 in this condition." (PMID 38067370, 2023). "The progesterone resistance and subsequent infertility seen in endometriosis seems to have an association with KLF9, a progesterone-receptor-interacting protein, as mice null for Klf9 are sub-fertile." (PMID 32575462, 2020). "The expression of KLF9 is lower in eutopic endometrium of women with endometriosis and endometrial KLF9 deficiency promotes endometriotic lesion establishment by the coincident deregulation of Notch-, Hedgehog-, and steroid receptor-regulated pathways." (PMID 26378916, 2015). "Our studies further showed that selective and specific loss of Klf11, in contrast to Klf9, was associated with the development of a characteristic phenotype that resembled advanced human endometriosis in a murine disease model." (PMID 23555910, 2013). "Furthermore, KLF9 deficiency in the uterus has been shown to promote the establishment of ectopic lesions in a mouse model of endometriosis." (PMID 26223982, 2015). "This approach has enabled us to use the system effectively not only for objectively evaluating the effect of loss of Klf11 or Klf9 on the pathogenesis of endometriosis, but also to investigate the effect of planned environmental and therapeutic interventions designed to arrest this process." (PMID 23555910, 2013). "KLF9 knockdown may underlie progesterone resistance in endometriosis." (PMID 39263604, 2024). "Loss of KLF9 may underlie progesterone resistance in endometriosis." (PMID 38513352, 2024). "The associations between diminished KLF9 expression, the activation of Notch signaling, and a loss of progesterone receptor protein levels in endometriotic lesions were confirmed in women with endometriosis and mechanistically in vitro using human endometrial stromal cells." (PMID 38067370, 2023). "Experimental endometriosis was then induced using endometrial tissue devoid of Krüppel-like factor 9 (Klf9), a key factor in progesterone receptor signaling." (PMID 38999965, 2024). "Moreover, loss of coregulation between KLF9 and PR may underlie the pathogenesis of endometriosis." (PMID 26223982, 2015). "For example, in the current study the Klf11-/- genetic background allowed us to define a novel role for this human disease-related gene in endometriosis in contrast to its paralog Klf9." (PMID 23555910, 2013). "In order to evaluate the specificity of Klf11 in the pathogenesis of endometriosis, we also surgically induced endometriosis in Klf9-/- mice." (PMID 23555910, 2013). "To confirm that the observed endometriotic phenotype in these knockout animals was specifically due to loss of Klf11-mediated transcriptional regulation, we also induced endometriosis in Klf9-/- animals." (PMID 23555910, 2013). "In eutopic endometrium from women with endometriosis, KLF9 mRNA was significantly reduced." (PMID 38513352, 2024). "Interestingly, KLF13-null lesions had no alterations in activity or readout in the Notch or Hedgehog signaling pathways when compared to corresponding wildtype lesions, indicating that KLF13 had less involvement than KLF9 in the pathogenesis of endometriosis." (PMID 38067370, 2023). "Nevertheless, the transcription factor, KLF9, has emerged as a potent player in reproductive dysfunctions associated with aberrant ER and/or PGR signaling, and several studies have investigated its relationship with endometriosis." (PMID 36428561, 2022). "When taken together with our earlier study using Klf9-null mutant lesions under the same dietary regimen, our findings suggest that dietary influences on endometriosis progression may be dependent in part, on lesion genotype." (PMID 34712146, 2021).
endometriosis (continued). "They reported that the loss of coregulation by KLF9 on WNT-signalling component expression, in human endometrial stromal cells, may account for progesterone resistance in endometriosis." (PMID 23843796, 2013). "miR-142-3p by regulating KLF9-mediated autophagy could suppress endometriosis in vitro and in vivo." (PMID 32850438, 2020). "Another mouse study of endometriosis showed that HFD increased lesion number and MΦ infiltration and proinflammatory and prooxidative stress-related genes in the lesion when Klf9 null donor endometrial fragments were inoculated as a donor tissue." (PMID 38559689, 2024). "Endometrial expression of Hoxa10, Hoxa11, Igfbp1, Klf9 (Kruppel-like factor 9) and PGR was reduced in mice when endometriosis was induced in the peritoneal cavity (proximal) compared to control eutopic endometrium." (PMID 36830705, 2023). "Furthermore, multiple studies have discovered that KLF9, KLF11, KLF12, KLF15, and KLF16 are all involved in the occurrence and development of endometriosis." (PMID 39263604, 2024). "In a mouse model of endometriosis, the absence of KLF9 promoted ectopic endometrial lesion establishment." (PMID 38067370, 2023). "In women with endometriosis, mRNA abundance of KLF9 in eutopic endometrium was lower than for women without endometriosis." (PMID 38067370, 2023). "Similarly, the absence of KLF9 in endometriotic lesions in a mouse model of endometriosis, led to increased OS both systemically and in lesions." (PMID 38067370, 2023).
breast carcinoma (14 papers, 2008 to 2025). "Studies have demonstrated significantly lower KLF9 expression in breast cancer tissues compared to benign tissues, which is associated with enhanced cell migration and invasion." (PMID 40860800, 2025). "In breast cancer models, gestational choline nutritional intervention was associated with elevated KLF9 expression in tumor tissues and altered metabolic-related genes (e.g., the oxidative stress regulator TXNIP)." (PMID 40860800, 2025). "This KLF9-NF-κB antagonism underscores a novel tumor-suppressive axis in breast cancer, where KLF9 deficiency promotes NF-κB-driven metastatic programs." (PMID 40860800, 2025). "Next to loss in invasive vs non-invasive cell lines, KLF9 also showed significantly lower expression levels in the “early” invasive cell population, in several public expression data sets and in clinical breast cancer samples when compared to normal tissue." (PMID 25593984, 2014). "The loss of KLF9, as found in several Oncomine breast data sets and in a series of breast samples from our institution, confirm the clinical relevance of this transcription factor in human breast cancer." (PMID 25593984, 2014). "Clinical research has also demonstrated that reduced KLF9 expression in breast cancer tissues is correlated with poorer prognosis." (PMID 40860800, 2025). "In breast cancer, KLF9 functions as a tumor suppressor, exhibiting inverse correlation with its expression and tumor aggressiveness." (PMID 40860800, 2025). "Restoration of KLF9 expression in breast cancer cell lines has been shown to suppress their invasive capabilities, suggesting its therapeutic potential for preventing metastasis." (PMID 40860800, 2025). "For example, KLF9 inhibits the invasiveness of breast cancer cells by regulating the transcription of E-cadherin." (PMID 40860800, 2025). "Specifically, in breast cancer patients, the expression level of KLF9 in cancer tissues was significantly lower than that in normal tissues, and its expression level was related to tumor size and clinical stage." (PMID 40860800, 2025). "In previous studies, KLF9 suppressed human breast cancer invasiveness by downregulating matrix metalloproteinase 9 transcription and suppressed the invasion and metastasis of gastric cancer cells by inhibiting the transcription of MMP28." (PMID 37370046, 2023). "Part of the suppressive effect of KLF9 on breast cancer promotion was suggested to involve its role in repressing E-cadherin expression and in supporting normal circadian physiology." (PMID 38067370, 2023). "In breast cancer cells, KLF9 recruits HDAC1 to the MMP9 (Matrix Metallopeptidase 9) gene promoter to repress MMP9 synthesis and consequent cell migration/invasion." (PMID 38067370, 2023). "This indicates that the MBNL1-AS1/miR-889-3p/KLF9 axis effectively reduces glycolysis in breast cancer cells and inhibits breast cancer progression." (PMID 37204526, 2023). "Recently, the oscillatory behavior of KLF9 has been explored within the context of KLF9 suppression in breast cancer." (PMID 38067370, 2023). "KLF9 gene and protein expression is lower in breast cancers when compared to paired normal tissue; moreover, KLF9 inhibited breast cancer cell proliferation and invasion in vitro and in vivo." (PMID 38067370, 2023). "Krüppel-like factor 9 (KLF9) blocks lung metastasis of breast cancer and increases CDH1 expression in 4T1 cells in vivo, indicating that the KLF9/CDH1 axis strongly contributes to breast cancer invasion and metastasis." (PMID 35464064, 2022). "The reduced expression of KLF9 has also been reported in breast cancer, human colorectal tumors, and hepatocellular carcinoma." (PMID 35047407, 2021). "Our results provide the first evidence of KLF9 as a suppressor of invasive growth in breast carcinoma." (PMID 25593984, 2014).